C17orf113 (chromosome 17 open reading frame 113)
Gene: Protein-coding gene on chromosome 17 (42,038,232 to 42,050,601, reverse strand). Ensembl gene ENSG00000267221.
Genetic constraint (gnomAD): Loss-of-function variants: 6 observed, 13.13 expected, observed/expected ratio (o/e) 0.46, 90% interval 0.25 to 0.9. The upper end of that interval is the gene's LOEUF score, 0.9, which puts it in group 3 of 6, group 1 being the genes least tolerant of losing a copy. Missense variants: 714 observed, 729.98 expected, observed/expected ratio (o/e) 0.98, 90% interval 0.92 to 1.04. Synonymous variants: 327 observed, 332.13 expected, observed/expected ratio (o/e) 0.98, 90% interval 0.9 to 1.08.
Homologues: Orthologues: chimpanzee C17H17orf113 (99% identical), macaque C16H17orf113 (98% identical), dog C17orf113 (91% identical), pig C17orf113 (91% identical), zebrafish zbtb8b (12% identical). Paralogues in human: ZBTB8B (13% identical), ZBTB22 (11% identical), ZBTB10 (9% identical), ZBTB8A (9% identical), ZBTB9 (9% identical).